PIM3 (Pim-3 proto-oncogene, serine/threonine kinase)
Diseases named in the same sentence as PIM3 in open-access papers (continued):
Sharing a sentence is not in itself a finding about the gene and the disease.
tumor (continued). "Moreover, tumor cell lines established from λ-Myc and Eμ-Myc transgenic mouse B cell tumors still exhibited elevated mRNA levels of Pim3, suggesting the importance of maintaining expression even in conditions of surplus growth factors." (PMID 21646687, 2011). "In addition, proteins with dysregulated expression in tumor cells, such as Bcl2, Pim3, PI3K/Akt, etc., could all mediate radiation resistance by affecting DNA damage repair in tumor cells." (PMID 36959858, 2023). "PIM3 was a member of the PIM family of oncogenic serine/threonine kinases, and it has established roles in cell proliferation, immune regulation, and tumor development." (PMID 41536518, 2026). "Inhibition of PIM3 effectively rescued CAR-T cells from the profound immunosuppressive effects of hypoxia, resulting in enhanced tumor-killing activity and prevention of recurrence in a solid tumor mouse model." (PMID 41199316, 2025). "PIM3 KO CAR-T cells demonstrated superior tumor control, leading to complete tumor regression in all treated mice, whereas wild-type CAR-T cells achieved tumor clearance in only four out of seven mice." (PMID 41199316, 2025). "Genetic or pharmacologic inhibition of PIM3 counteracted hypoxia-induced impairment, enhancing memory phenotypes of CAR-T cells, and improving their anti-tumor activity both in vitro and in vivo." (PMID 41199316, 2025). "Knocking out PIM3 conferred resistance to hypoxia-induced dysfunction and significantly improved CAR-T cell-mediated tumor clearance." (PMID 41199316, 2025). "Normoxia-cultured WT CAR-T or PIM3 KO CAR-T treatment was administered on day 12 post-tumor implantation, and blood, tissue, and tumor samples were collected on day 10 post-treatment for analysis." (PMID 41199316, 2025). "To investigate the broader impact of PIM inhibition on tumor metastasis and leakage, we used the 4T1 and LLC tumor cell lines, which expressed Pim3 and 4T1 additionally high levels of Pim1." (PMID 39627185, 2024). "While only the FOXM1, PYROXD1, hTERT and MCTP1 genes were overexpressed in CRC tumor tissues relative to the normal adjacent tissues at all the stages, but FOXM1, PYROXD1, hTERT, PIM3, BMI1, PPARA and MCTP1 were found to have stage-dependent expression." (PMID 35845311, 2022). "In a previous study, we demonstrated that a small hairpin RNA (shRNA) plasmid silencing Pim-3 expression can induce apoptosis of HCC cells and inhibit tumor proliferation, suggesting potential utility of Pim-3 kinase as a candidate target for HCC therapy." (PMID 29069816, 2017). "Therefore, a tumor that expresses a high level of Pim-3 may be more resistant to chemoradiotherapy." (PMID 29167471, 2017). "Ubenimex inhibits the expression of the proto-oncogene, Pim-3, which is accompanied by decreased expression of BCL-2 and BCL-XL, decreased phosphorylation of Bad, and increased tumor apoptosis." (PMID 29069816, 2017). "In addition to improved phenotypes and tumor-killing efficiency, hypoxia-conditioned PIM3 KO CAR-T cells also secreted more IFN-γ, TNF-α, and granzyme B after being stimulated with tumor cells." (PMID 41199316, 2025). "Targeting PIM3 delays tumor growth in in vivo tumor models with no side effects, suggesting that PIM3 is an excellent therapeutic strategy for some solid cancers." (PMID 38339286, 2024). "We focused on PIM3, since limited data is available on the role of PIM3 in ECs46, whereas cancer cell expressed PIM kinases are well-known oncogenes, which promote cancer cell motility, metabolism, proliferation as well as metastasis and tumor angiogenesis." (PMID 39627185, 2024). "Interestingly, the expression of PIM3 and INHBB was increased in sorted HUVECs 16 h after coculturing with tumor cells, as compared to HUVEC monocultures, indicating that tumor cells were sufficient to induce upregulation of rCap markers." (PMID 39627185, 2024).
tumor (continued). "We found that CD8-GNLY effector T cells in high tumor infiltration group displayed increasing level of the serine/threonine kinase PIM family (PIM2 and PIM3), NR4A2/3, KLF4/6, BCL2, GPR183 and COTL1 compared to the ones from HD and low tumor infiltration group." (PMID 36532059, 2022). "The rate of PIM3 expression did not increase in tumor tissues in contrast to relative to the adjacent normal tissues P (H) = 0.335." (PMID 35845311, 2022). "Compared with unmodified wild-type (WT) CAR-T cells, PIM3 KO CAR-T cells exhibited a higher proportion of memory phenotypes and a lower proportion of TTE cells after six days of hypoxia treatment, as well as significantly improved tumor-killing persistence in long-term killing assays." (PMID 41199316, 2025). "The lack of Pim2 and Pim3 reduced tumor-induced bone invasion by 70%, and this reduction is comparable to the reduction of tumor-induced bone invasion in the absence of all three isoforms, although the absence of all three isoforms is necessary to achieve the maximum effect." (PMID 24860787, 2014). "Our results revealed the tumor-induced endothelial JAK-STAT-PIM-BCL3 axis both in vitro and in vivo, with upregulation of also Pim1 in rCap, albeit less than Pim3, whereas Pim2 was not expressed in the lung ECs." (PMID 39627185, 2024). "While CAPZA1, CAPZA2 and CAPZB, but not CAPZA3 levels correlated well with PIM1 levels in all tumor tissues, similar correlations were also observed for PIM2 and PIM3 in the samples with high Gleason scores." (PMID 32771000, 2020). "In the TCGA_LIHC cohort, 16 of 120 genes were downregulated in HCC tissue rather than in adjacent non-tumor tissue, and 9 of 16 genes, namely, ALDH8A1, C11orf96, CLYBL, EFNB3, ENG, NPC1L1, PIM3, SEC14L2, and SLC8A1, displayed a significant difference (p < 0.05)." (PMID 33352935, 2020).
cancer (27 papers, 2009 to 2025). A tumor composed of atypical neoplastic, often pleomorphic cells that invade other tissues. "PIM kinases, including PIM1, PIM2, and PIM3, are serine/threonine kinases frequently overexpressed in tumors and contribute to cancer cell proliferation, survival, and metastasis." (PMID 41199316, 2025). "PIM3 proto-oncogene is frequently overexpressed in various human cancers, including hematological malignancies and solid tumors, and its expression is associated with poor clinical outcomes and shorter patient survival." (PMID 38339286, 2024). "This review provides an overview of recent developments and insights into the role of PIM3 in various cancers and its potential as a novel molecular target for cancer therapy." (PMID 38339286, 2024). "Silencing PIM3 inhibits the proliferation of various cancer cell lines in vitro and promotes apoptosis." (PMID 38339286, 2024). "More recent studies demonstrate PIM involvement in cancer cell migration and metastatic invasion, and PIM3 was also shown to colocalize with FAK at the lamellipodia." (PMID 37084168, 2023). "Pim3 is barely expressed in normal tissues but is highly expressed in the prostate, large intestine, liver, and other cancer tissues." (PMID 37592331, 2023). "Pim3 knockout led to the activation of signaling pathways that were related to cancer, HTLV-1 infection, and neural synapses, while its absence repressed pathways related to metabolism, proteasome, and spliceosome." (PMID 36150380, 2022). "Together, these findings highlight the role of PIM3 in contributing to cancer cell stemness and cisplatin insensitivity." (PMID 33727604, 2021). "The PIM1, PIM2, and PIM3 serine/threonine kinases play a role in the proliferation and survival of cancer cells." (PMID 31073371, 2019). "To ascertain the broader applicability of these findings, we determined the effects of rapamycin on PIM3 in human cancer cell lines that exhibit growth factor-independent mTORC1 activation and varying levels of PIM3." (PMID 29170467, 2017). "PIM protein family, short-lived serine/threonine kinases (PIM1, PIM2 and PIM3), are weak oncogenes but contribute to tumorigenesis as cancer targets." (PMID 25749522, 2015). "Aberrant Pim3 expression in cancer cells mediates its anti-apoptotic effects by phosphorylating Bad." (PMID 19300518, 2009). "PIM-3 silencing reduces the growth of several types of cancer cells in vitro by inducing apoptosis." (PMID 38339286, 2024). "However, PIM3 has been shown to be highly expressed in premalignant lesions and malignant tumors of these organs." (PMID 35892829, 2022). "The knockdown of PIM3, using short interfering RNA (siRNA) or short hairpin RNA (shRNA), has been shown to enhance apoptosis and decrease in vitro survival of various types of human cancer cells, such as colon, pancreatic, and HCC." (PMID 35892829, 2022). "Furthermore, Pim-3 contributes to chemoradiotherapy resistance by attenuating G2/M cell cycle arrest in cancer cells." (PMID 29167471, 2017). "Furthermore, induction of PIM3 by rapamycin was also observed in a variety of human cancer cell lines." (PMID 29170467, 2017). "Using the criteria of circadian proteomic expression, circadian expression in multiple tissues and independent gene knockdown data, we propose six genes (Por, Mtss1, Dgat2, Pim3, Ppp1r3b, Upp2) involved in metabolism and cancer for further experimental investigation." (PMID 26576534, 2015). "This is potentially significant, since PPARγ is also highly expressed in many cancers and therefore may play a role in inhibiting apoptosis via Pim3 expression." (PMID 19300518, 2009). "Overall, developing PIM3-specific inhibitors or combination therapies that target PIM3 along with other resistance-related pathways could be a promising approach to improving cancer treatment outcomes." (PMID 38339286, 2024).
cancer (continued). "The identification of safe, selective, potent, and effective PIM3 inhibitors provides a foundation for clinical translation and may have a significant clinical impact on the treatment of some solid and hematological cancers by offering new hope for patients with PIM3-driven cancers." (PMID 38339286, 2024). "Following a random selection of the cancer-related genes PIK3C3, PIM3, and PTEN, the researchers discovered that the cancer had progressed." (PMID 35154620, 2022). "TCI identified 6 such SGA-FIs, including some well-known cancer drivers, such as PTEN and NEFH, and potential cancer drivers mentioned in recent studies, such as TLK2, USP13, and PIM3." (PMID 31276486, 2019). "We identified more novel interacted proteins with PIM kinases (PIM1, PIM2 and PIM3) and further shed light on more molecular mechanisms of PIM kinases in cancer." (PMID 25749522, 2015). "The barrier-protective role of PIM3 and the effect of PIM inhibitor on vascular permeability may partly explain the limited efficacy of PIM inhibitors in cancer trials." (PMID 39627185, 2024). "In concordance, Pim3, Bcl3 and Inhbb were upregulated in lung ECs 14 d, but not 7d after cancer cell inoculation." (PMID 39627185, 2024). "Thus, our results suggest that cancer reactive EC marker, PIM3, protects the EC barrier during cancer cell colonization, while PIM inhibition increases vascular leakage and lung colonization by different cancer types." (PMID 39627185, 2024). "The metabolic consequences of decreased miR-33 and subsequent increase in PIM3 and PIM1, therefore, might also influence the cellular and systemic responses to mTOR inhibitors in cancer and other disease settings." (PMID 29170467, 2017). "A canonical cancer pathway involving the NFkB complex is central to this network, which is predicted to activate (denoted by orange relationship lines) various genes upregulated in the dataset, including the transcription regulator CITED4, peptidase ADAMTS9, and kinase PIM3." (PMID 32414099, 2020). "In this pilot study, we tested our hypothesis by examining whether the mRNA expressions of three randomly selected cancer-related genes PIK3C3, PIM3, and PTEN were correlated during cancer progression and the correlation coefficients could be used for cancer diagnosis." (PMID 24818135, 2014). "However, PIM3 expression was found to be not significant in the other stages of cancer." (PMID 35845311, 2022). "Thus, radiation may not be as effective against cancers overexpressing PIM3." (PMID 38339286, 2024).
hematological cancers (3 papers, 2023 to 2024). "This would explain why Pim-3 is highly over-expressed in some solid cancers, such as prostate and breast cancer, while Pim-1 and Pim-2 are generally over-expressed in hematopoietic cancers." (PMID 36694243, 2023). "The over-expression of Pim kinases is largely specific to hematologic cancers compared to solid tumors, though exceptions do exist, particularly regarding Pim-3." (PMID 36694243, 2023). "The development of selective and effective PIM3 inhibitors may have a significant clinical impact and a novel potential therapeutic strategy for PIM3-driven solid and hematological cancers." (PMID 38339286, 2024). "The PIM family consists of three members, PIM1, PIM2, and PIM3, from which PIM1 and PIM3 have been shown to be upregulated in solid cancers, while PIM2 mostly in hematological cancers." (PMID 37943821, 2023). "Although pan-PIM inhibitors have entered clinical trials in hematological cancers, they were not potent or specific enough or exhibited side effects; thus, currently, there is no FDA-approved inhibitor for targeting all PIMs or PIM3." (PMID 38339286, 2024).
hematologic malignancies (2 papers, 2015 to 2023). "Pim‐1 is overexpressed in hematologic diseases and solid tumors, pim‐2 in myeloma, lymphoma, and leukemia, and pim‐3 in substantial organ tumors." (PMID 37162273, 2023). "The family of pim kinases comprises three isozymes: pim‐1, pim‐2, and pim‐3, all of which are reported to be overexpressed in several hematologic malignancies." (PMID 37162273, 2023).
heart disease (1 paper, 2023). "Pim3 is functionally responsive to forskolin, a cAMP activator that is also dietary supplement for weight loss and heart disease." (PMID 37162190, 2023).
infection (1 paper, 2026). The state of being infected such as from the introduction of a foreign agent such as serum, vaccine, antigenic substance or organism. "PIM kinases (PIM1, PIM2, PIM3) are serine/threonine kinases implicated in infection and reactivation of various viruses, but their roles in HIV-1 gene expression and particle production remain unclear." (PMID 41754420, 2026).
PIM3 also shares sentences with these, for which no sentence is quoted: adenocarcinoma (2 papers); mantle cell lymphoma (2); metabolic disease (2); multiple myeloma (2); acute myeloid leukemia (1); Burkitt lymphoma (1); demyelinating disease (1); dependence (1); diabetes mellitus (1); Distal Muscular Dystrophy (1); follicular lymphoma (1); gastric adenoma (1); gastrointestinal tumors (1); heart failure (1); immune diseases (1); large cell neuroendocrine carcinoma (1); lung (1); lung adenocarcinoma (1); lung tumors (1); myocardial ischemia (1); myopia (1); neuroendocrine carcinoma (1); ovarian carcinoma (1); septic shock (1); small cell lung carcinoma (1); thyroid cancer (1); type 1 diabetes (1); type 2 diabetes mellitus (1); Uterine leiomyoma (1); viral infection (1).